TCF4 (transcription factor 4)
Diseases named in the same sentence as TCF4 in open-access papers (continued):
Sharing a sentence is not in itself a finding about the gene and the disease.
cancer (continued). "In addition, up‐regulation of miR‐125b levels via Snail‐activated Wnt/β‐catenin‐TCF4 pathway in Snail‐overexpressing breast cancer cells is found to increase cancer stem cell population and confer Taxol chemoresistance during cancer treatment." (PMID 33332677, 2021). "Moreover, the transcription factor CUX1, by targeting key subunits of the Wnt/β-Catenin pathway, showed a positive correlation with mRNA expression of Axin2, CTNNB1, and TCF4 in most normal and cancer tissues or cell lines." (PMID 34422906, 2021). "We thus conclude that NRF3 is induced by the β-catenin/TCF4 complex in human cancer cells." (PMID 31288376, 2019). "The Wnt/β-catenin/TCF4 pathway plays critical roles in cancer progression." (PMID 31659154, 2019). "In addition to Akt, β-catenin translocates into the nucleus and binds transcription factor TCF4 and serves as a transcriptional activator, inducing cancer cell proliferation and migration." (PMID 31355268, 2019). "In this study, the TCF4 immunostaining scores were found to be significantly lower post-therapy (Wilcoxon matched-pairs signed-rank test P=0.009), further supporting the link with cancer adaptation to chemotherapy." (PMID 29666142, 2018). "In this pathway, TCF4, also called TCF7L2, forms a complex with beta-catenin, and the beta-catenin–TCF4 transcription factor complex binds preferentially to the cancer risk-associated rs6983267 (G) allele in vivo and in vitro leading to a two-fold change in c-MYC expression." (PMID 29232378, 2017). "We are next to study whether enhancing Wnt signaling by overexpression of TCF4 affects the growth of cancer cells or normal cells." (PMID 28570681, 2017). "In many cancer cells, TCF4/TCF7L2 is localized to the nucleus." (PMID 28536608, 2016). "The transcription factor, TCF4, which facilitates this enhancer-promoter interaction has differential binding affinity at the MYC enhancer depending on the allele of this established cancer variant rs6983267." (PMID 25658610, 2015). "We used resveratrol for the further study to investigate the role of TCF4 in cancer prevention." (PMID 25961950, 2015). "Therefore, we tested if other phytochemicals possessing anti-cancer activity negatively affect the expression of TCF4." (PMID 25961950, 2015). "Therefore, it is reasonable that TCF4 is considered a general target for many anti-cancer compounds." (PMID 25961950, 2015). "Accordingly, one can speculate that the constitutively active β-catenin-TCF-4 pathways would either enhance FasL promoter activities in human cancer cells or enable cancer cells to express FasL through binding to FasL TBEs." (PMID 22022540, 2011). "A PLD inhibitor that suppresses binding of TCF-4 to β-catenin could be very valuable as a new chemopreventive drug in treatment of certain forms of cancer." (PMID 20711340, 2010). "There is evidence that targeting TCF-4 could restrain the progression of cancer." (PMID 34617205, 2022). "However, the functional role of the TCF4/TWIST1 complex in PTHrP-associated cancer cachexia has not been previously investigated." (PMID 35406121, 2022). "This study identifies a new function for class I bHLH transcription factors (e.g., TCF3, TCF4, and TCF12) that are important in cancer and development." (PMID 39119816, 2025). "β-catenin is well-known in promoting cancer stemness and EMT, and has been reported to activate DCLK1-L transcription by binding to TCF4/LEF elements within the α-promoter." (PMID 40775208, 2025). "Heterozygous and homozygous amplification and deletion of TCF4, TCF3, and TCF7 were detected in pan-cancer patients." (PMID 39205642, 2024). "Our preliminary data suggest nuclear βPix binds β-catenin/TCF4 transcription complexes, augmenting key β-catenin target gene expression, e.g., PTGS2, important for cancer progression." (PMID 37805544, 2023). "A pan-cancer view revealed that LEF1, TCF3,TCF4, and TCF7 have aberrant expression andare potentially involvement in the tumorigenesis of various cancer types." (PMID 38100720, 2023).
cancer (continued). "These progenitor cancer cells presented alterations of key transcription factors such as SOX4 (SRY-Box Transcription Factor 4), SOX11 (SRY-Box Transcription Factor 11), and TCF4 (Transcription Factor 4)." (PMID 35875065, 2022). "In our study, we observed that H. pylori leads to the high antioxidant status of cancer cells by upregulating GPX4 expression and activity via TCF4." (PMID 35534546, 2022). "In the future, prospective studies of ETS1 and TCF4 expression and their role in immune invasion of human cancers are needed, and a novel antitumor immunotherapeutic agent targeting ETS1 and TCF4 is successfully developed and tested." (PMID 34686186, 2021). "MANOVA on these genes reveals that this combined set of 7 genes (MYC, CD40LG, CCL4, IL7, TCF4, CCR7 and FASLG) is together statistically significantly reliant on both time post-exposure (p = 0.042) and cancer type (p < 0.001)." (PMID 33941218, 2021). "Other studies have shown that ARRB1 regulates several cancer-related cellular processes via diverse signal transduction pathways, including the Ras/Raf/MEK/ERK family, β-catenin/TCF4 signalling, Akt/GSK3β signalling, mTOR signalling and NF-κB signalling." (PMID 34380537, 2021). "Our data demonstrated that TCF4, a WNT signaling component capable of mediating TGF-β signaling and promoting EMT in various cancers, directly bound to the ERLR promoter region and activated its expression." (PMID 33664479, 2021). "In detail, the activity of NF-YA, STAT3, TCF4 and WT1 isoforms in cancers has been documented and proposed for cancer molecular stratification." (PMID 32244895, 2020). "Mechanistically, TCF4/LEF1 forms a complex with β-catenin to bind its target gene promoters and promote cancer cell proliferation." (PMID 29765046, 2018). "Analysis of more than 200 CRC specimens revealed that the TCF4 gene was inactivated in 31% of microsatellite-unstable (MSI) and 12% of microsatellite-stable (MSS) cancers." (PMID 30200414, 2018). "In cancer cells, Sox9 and Krüppel-like factor 4 (KLF4) interact with β-catenin and reduce its binding to TCF4 and showed anti-oncogenic activity by inhibiting the activity of the Wnt/β-catenin signaling pathway." (PMID 28279198, 2017). "By interaction with downstream transcription factors, such as TCF4 or Lef-1, the β-catenin/Lef/TCF complex was formed which impacts the transcription activity of multiple genes that are involved in cancer survival, metastasis, and apoptosis." (PMID 27801803, 2016). "Many bHLH transcription factors, such as Twist1, TCF4, DEC1, have been reported to act as strong promoters of EMT and metastatic spread in many human carcinomas." (PMID 27384482, 2016). "We additionally report an important role of β-catenin and TCF4/LEF binding-sites for activating (α)-promoter, while activated NF-κBp65 (bound to NF-κB-cis-element), activates (β)-promoter in cancer-cells." (PMID 26447334, 2015). "Through the interaction with TCF4 and β-catenin, TNIK phosphorylates TCF4 at serine 154, and mediates the activation of Wnt target genes that are involved in cancer cell growth." (PMID 25337707, 2014). "PI3K (phosphoinositide 3-kinase)/Akt and β-catenin/TCF-4 signaling pathways have been reported to play important roles in EMT and cancer progression." (PMID 23826359, 2013). "Our findings reveal a previously unknown role of TCF4 in recruiting factors that enhance MYC activity to CRC heterodimerization partners and a novel understanding of TCF4's function in development and cancer." (PMID 39119816, 2025).
cancer (continued). "An interesting observation in multi-transcript genes is worth noting; first, the highest number of transcripts per gene that correlated with a phenotype in a cancer type was 19, and was limited to the CD36 (19 out of 24 transcripts), ABI3BP (19/29), and TCF4 (19/93) genes." (PMID 41048343, 2025). "The TCF4 and AP-1 downstream gene CD44, a protein that is expressed on the cell surface in cancer stem cells, interact with PKM2, and thereby strengthen the glycolytic phenotype of hypoxic cancer cells." (PMID 37553596, 2023). "TCF4–TWIST1 interaction regulates TGFβ1 signalling-induced EMT and cancer metastasis." (PMID 35406121, 2022). "The mechanisms underlying the interaction between TCF4 and TWIST1 and the role of the TCF4–TWIST1 complex in cancer cachexia have not been investigated." (PMID 35406121, 2022). "In HCC, an important regulatory axis related to SE was found: transcription factor 4 (TCF4) occupies the SE region and induces extensive interactions between SE and the AJUBA promoter, which strongly promotes AJUBA expression and increases cancer metastasis." (PMID 34011395, 2021). "Additionally, association analysis of CMTM6 mRNA levels with Wnt target genes (TCF4, LEF1, CD-44, MMP14, ENC1, ID2, PPARA, and JAG1) from the cancer genome atlas HNSCC cohort using GEPIA showed a positive correlation (r > 0.2)." (PMID 33434185, 2021). "LEF1 is a transcription factor that promotes the canonical Wnt/β-catenin signaling pathway by cooperating with TCF4 and is pathologically involved in cancer development and progression in multiple cancer types." (PMID 32933177, 2020). "Our present study identified that the β-catenin/TCF4 complex in the Wnt signaling pathway activates NRF3 mRNA expression, consequently leading to the upregulation of cell proliferation and GLUT1 gene expression in cancer cells." (PMID 31288376, 2019). "TCF4/β‐catenin binding in the GLUT3 gene occurs at the end of intron 2, in the same intron, and only ~250 bp after the ZEB1 binding site, demonstrating a central regulatory role for this intragenic enhancer in cancer cells." (PMID 28923827, 2017). "Whether FOXO3a regulating doxorubicin-induced EMT in HCC via changing the interaction of β-catenin/TCF4 complex, which was involved in the EMT process of various cancers, was investigated in the following study." (PMID 25871400, 2015). "However, in cancer cells Wnt stimulation increases the protein level of β-catenin and YAP in the nucleus and recruits them to the promoter regions of the RMRP gene via TCF4 and TBX5 DNA binding proteins, which leads to elevated transcription of RMRP." (PMID 26415221, 2015). "Consistent with MACE results, CTHRC1, TCF4 and ZEB1 were significantly higher expressed in PDAC compared to normal pancreas tissues, with median normalized Ct (ΔCt) values between −1.8 and 1.8 in cancer- and 3.1-5.1 in normal tissues." (PMID 25910082, 2015). "Thus, Tcf-4 overexpression in a Wnt-positive background upregulates OPN, resulting in high levels of both Tcf-4 and OPN, thereby promoting cell invasion and cancer progression." (PMID 21772333, 2011). "GPX4 is the ferroptosis core gene, and one recent study speculated that Targeting Wnt/β-catenin signaling by using inhibitors or knocking down TCF4 inhibited the expression of GPX4 and promoted the sensitivity of cancer cells to chemotherapy-induced ferroptosis." (PMID 37031292, 2023). "Additionally, CtBPs may directly coactivate TCF4/LEF at key target promoters (c-Myc, LGR5) to promote cancer stem cell self-renewal." (PMID 35299743, 2022). "Based on these data, TCF4 may be considered a promising target for GBM treatment, to be therapeutically suppressed to ignite CSC differentiation, reduce cell malignancy, and even sensitize cancer cells to drugs." (PMID 35454804, 2022).
cancer (continued). "However, the majority of tumors which expressed TCF-4 protein were low expressers or had reduced expression of TCF-4 protein, which suggested that the expression of TCF-4 protein was significantly reduced during transition from normal epithelium to carcinoma." (PMID 32265994, 2020). "However, because few reports have described the mechanisms mediating Wnt signaling activation in ESCC, the factors that regulate TCF4/TCF7L2 expression in this type of cancer are not known." (PMID 28536608, 2016). "Our data support a direct role of β-catenin/TCF4 in the regulation of RHBG expression in this cell line, and further indicate that RHBG could serve as a direct reporter of the Wnt/β-catenin pathway in specific cancer cell contexts." (PMID 26029888, 2015). "The results showed that henryin strongly inhibited the binding of TCF4 to β-catenin in a dose-dependent manner in SW480 cells but not its analogs enmenol and minheryin C, which is consistent with the inhibitory activities on the Wnt signaling and the cancer cell growth of the compounds." (PMID 23844215, 2013). "However, the clinical roles of TCF4 in cancer cachexia have not been previously investigated." (PMID 35406121, 2022). "Although containing β‐catenin‐binding capacity in hyperactive β‐catenin cancer cells, TCF4N has demonstrated to be a β‐catenin‐TCF4 independent regulator in GBM, which neither binds β‐catenin nor alters its cellular distribution and activation." (PMID 36116131, 2022). "In view of cancer cell fate, it is not surprisingly that overexpression of RANKL by PC3 cells led to increased binding of β-catenin to TCF4 and to increased TOP activity." (PMID 34108600, 2021). "Thus, Tcf-4 overexpression in a Wnt-negative background fails to upregulate OPN, resulting in a high level of Tcf-4 but a low level of OPN, thereby suppressing cell invasion and cancer progression." (PMID 21772333, 2011).
neurodevelopmental disorder (43 papers, 2011 to 2025). A behavioral and cognitive disorder with onset during the developmental period that involves impaired or aberrant development of intellectual, motor, or social functions. "Together, our findings highlight a previously unappreciated role for Tcf4 in regulating astrocyte allocation, offering additional insights into the mechanisms underlying neurodevelopmental disorders linked to Tcf4 mutations." (PMID 39300210, 2024). "Intriguingly, several of the predicted TCF4 interactors have been linked to neurodevelopmental disorders featuring corpus callosum abnormalities, suggesting a pathophysiological relevance of the proposed TCF4 TF network." (PMID 34184026, 2021). "Transcription Factor 4 (TCF4) binding sites were found in a large number of neuronal genes that were implicated as genetic risk factors for common neurodevelopmental disorders." (PMID 31649562, 2019). "A single SNP in Transcription Factor 4 (TCF4, chromosome 18), believed to be important in nervous system development and previously associated with neurodevelopmental disorders and psychiatric diseases, was also associated with SRH." (PMID 27864402, 2017). "Furthermore, a rare mutation in TCF4 leads to Pitt–Hopkins syndrome, a rare neurodevelopmental disorder." (PMID 34680902, 2021). "Nevertheless, our findings strongly support a major role of CHD8 on Wnt/β-catenin signaling, and a connection between CHD8 and TCF4, and several other genes that have been implicated in neuropsychiatric and neurodevelopmental disorders, in particular, members of the DLX gene family." (PMID 28321286, 2017). "In this study, we showed TCF4 is preferentially expressed in cortical interneurons during early neural development, indicating the perturbed biology by TCF4 genetic variants at this particular spatiotemporal point would play an assignable role in neurodevelopmental disorders." (PMID 35965434, 2022). "Therefore, disruptions of interneuron development might be the underlying contribution of TCF4 perturbation to a range of neurodevelopmental disorders." (PMID 35965434, 2022). "Group 1—Severe multisystem neurodevelopmental disorders (Transcriptional/RNA-processing phenotype): This group included patients carrying variants in POLR1C, TCF4, HNRNPU, NIPBL, and ACTG1." (PMID 41300846, 2025). "This suggests there is a link between TCF4 perturbation and neurodevelopmental disorders which must be investigated." (PMID 35965434, 2022). "We now investigated possible functional links between TCF4, MEF2C, ZEB2, UBE3A and ATRX which are all implicated in clinically overlapping, severe human neurodevelopmental disorders." (PMID 31988313, 2020). "Computational analyses of gene/mRNA regulatory interactions implicate known neurodevelopmental disorder risk genes (CHD8, TCF4, FMRP, BCL11B and TBR1) as regulators of this cascade and reveal pathways through which they may contribute to disease." (PMID 35031607, 2022).